CD28 (CD28 molecule)
Diseases named in the same sentence as CD28 in open-access papers (continued):
Sharing a sentence is not in itself a finding about the gene and the disease.
tumor (continued). "To further identify which amino acids sustained mTORC1 activity in CD8+ TILs, we isolated CD8+ TILs from the MC38 tumor model and stimulated the cells with anti-CD3 and anti-CD28 antibodies in medium depleted of individual amino acids." (PMID 33883257, 2021). "Mice were inoculated with CD73-negative B16.gp33 tumor cells and CD73 expression on CD28−CD8+ and CD28+CD8+ T cells in tumor-draining lymph nodes and tumor were analyzed." (PMID 34011962, 2021). "r2820, a BsAb targeting CD28 and CD20, induces T cell activation in peripheral blood mononuclear cell (PBMC) cultures of healthy donors and CLL patients and kills CD20+ tumor cells." (PMID 34358141, 2021). "We then compared the anti-tumor activity of A20-2G CAR T cells and A20-4G CAR T cells, containing the CD28/CD3ζ and CD28/4-1BB/CD27/CD3ζ signaling domains, respectively." (PMID 33763382, 2021). "In naive/Tcm CD4 T cells, there was reduced expression of CD28, ICOS, and OX40 in tumor compared with normal, with little PD1 expression and reduced CTLA4 expression in tumor T cells." (PMID 34936871, 2021). "Phagocytosis of dying tumor cells and mature DCs play an active immune role, so we stimulated the proliferation of T-cell receptors (CD3/CD28) using a medium with DCs cocultured with tumor cells under such conditions." (PMID 34336153, 2021). "In this regard, simultaneous multiple interaction T cell engagers (SMITEs) were designed that are composed of two independent BiTEs to enable concurrent recognition of two different TAAs on the tumor cell and of CD3 and CD28 on the effector T cells." (PMID 34885176, 2021). "A better selection of starting biological product using either anti-CD3/CD28 bead activation for CD3+ cell selection or specific immunomagnetic CD4+ and CD8+ sorting will avoid bringing tumor cells into the production process." (PMID 33414517, 2021). "Subsequently, second-generation CARs containing an additional co-stimulatory signaling molecule, such as 4-1BB, CD28, CD27, OX40 or ICOS have been developed to stimulate an endogenous immune response against tumor cells via epitope spreading." (PMID 33442419, 2021). "Low levels of CD80 expression serve as a mechanism of tumor escape from immune surveillance due to a higher affinity and, therefore, preferential binding of CTLA-4 to CD80 compared with that for CD28." (PMID 33923750, 2021). "Then, we activated tumor-infiltrating CD+ T cells through anti-CD3, anti-CD28, PMA and Ionomycin in vitro for 12 h." (PMID 33934206, 2021). "CD28 are a very important co-stimulatory marker, which is required as a secondary signal for activated CD8+ T cells and CD4+ T cells exerting anti-tumor response." (PMID 34488711, 2021). "Recent studies have highlighted the presence of CD28 and CTLA-4 on the surface of tumor-infiltrating NK cells in several mouse models of solid tumors." (PMID 34572799, 2021). "Our study of the B16.gp33 tumor model points to the fact that both CD28−CD8+ and CD28+CD8+ T cells exist in draining lymph nodes and solid tumors and that CD73-expressing CD28−CD8+ T cells can be a source of adenosine." (PMID 34011962, 2021). "Among these biomarkers are those related to the tumor microenvironment such as tumor infiltrative lymphocytes (TILs) or interferon signaling, CD8 + PD − 1 + Tcells expressing CD28 and gut microbiome in the feces." (PMID 33066479, 2020). "Previous studies suggested that PD-1 antibodies rely on the activation of the CD28/B7 pathway to rescue the depletion CD8+ T lymphocytes and then achieve anti-tumor effects." (PMID 32528882, 2020). "The third generation of CARs consists of activated domains and multiple co-stimulative domains; for example, joining the two domains of CD28, CD27, and OX40 (CD134), boosts the efficiency of CAR T cells to recognize tumor cells." (PMID 33167514, 2020). "This study suggested that the IL-15-conjugated CD28-CAR structure reduced the exhaustion marker and improved the persistence and the tumor-killing activity of NKT-established CARs." (PMID 33322408, 2020).
tumor (continued). "In monitoring the percentages of T cell subpopulations, the proliferation of lymphocytes in draining lymph nodes from tumor-bearing Siah2−/− or WT mice was assessed prior to and following stimulation in culture with CD3/CD28 antibodies combined with IL2." (PMID 31911617, 2020). "We show that a FAK inhibitor can shift this balance in favor of CD80 - CD28 interaction, promoting an anti-tumor immune response that is dependent on both CD80 and CD28." (PMID 31959281, 2020). "TILs functionality was tested in tumor-isolated lymphocytes following in vitro stimulation with anti-CD3 and anti-CD28." (PMID 32144446, 2020). "Predicted genes targeted by dysregulated oncomiRs or tumor suppressor miRNAs were mainly involved in cell cycle regulators such as CAPRIN1, CDC42, PTEN, IGF1R, BRCA1 and CD28, thereby controlling cancer dormancy." (PMID 33374139, 2020). "Conversely, while sustaining Treg survival and function, IL-2 induced by CD28 activation of LCK and autocrine signaling through IL-2 receptor on tumor-specific effector T cells appears to be crucial to counteract the inhibitory effects of TGF-β." (PMID 32625204, 2020). "For the second generation CAR design, 4-1BB-incorporated CAR-T cells show milder activation and longer persistence than CD28-incorporated CAR-T cells, which leads to enhanced in vivo efficacy in preclinical tumor models." (PMID 33281809, 2020). "When ACR or CAR was expressed in effector T cells, it activated T cells effectively by costimulating CD28 and CD137 (4-1BB) upon engagement of PD-L1+ tumor cells." (PMID 32637575, 2020). "Two second-generation, CD28 or 4-1BB, anti-B7-H3 CARs were able to completely reject PANC1 orthotopic tumors, with all mice remaining tumor-free for more than 80 days." (PMID 35582441, 2020). "One such MM-specific model targets CD38 on the tumor cell, and stimulates both CD3 and CD28 on the T cell." (PMID 32391000, 2020). "PMN-MDSCs isolated from tumor inhibited the proliferation of activated autologous CFSE-labeled T cells and IFN-γ production in medium containing CD3 and CD28." (PMID 32849517, 2020). "When comparing the novel NKG2D/2B4/CD3ζ CAR-NK cells to T cells transduced with the CD28/4-1BB/CD3ζ CAR, both demonstrated very similar anti-tumor activity, fortifying the importance of vehicle-specific CAR design." (PMID 32429316, 2020). "The activation of CTL relies on two signals: tumor antigen presented by the antigen presentation cell (APC) and co‐stimulatory molecules, especially CD28, located on the surface of the T cell." (PMID 32931665, 2020). "At each dose level, CD28-, 41BB-, and MC-CAR T cells induced tumor regression, resulting in a significant survival advantage (P < 0.001) in comparison with control mice." (PMID 33148882, 2020). "These consisted of miR‐326, miR‐155, p16INK4a, Gal‐9 and IP‐10 for age and p16INK4a, CD3+CD16+, CD8+CD57+, CD28+CD27−CD28− and whole tumor proportion of FOXP3+ cells for the G8 groups." (PMID 33024560, 2020). "In order to investigate the impact of cytokines released from 3A1low or 3A1high (Ctr for HCC) cells on the tumor microenvironment, we co-cultured PBMCs with conditioned media (CM) of tumor cells in the presence of anti-CD3/CD28." (PMID 31817719, 2019). "We show that co-targeting sMIC with a nonblocking antibody provides antigen-specific CD8 T cells with NKG2D and CD28 dual co-stimulation, in addition to elimination of inhibitory signals, and thus amplifies antigen-specific CD8 T cell anti-tumor responses." (PMID 31446896, 2019). "In consideration of the role of ICOS, CD28 and CD80 genes in tumor immunity, we chose ICOS rs4404254 T>C, rs10932029 T>C, CD28 rs3116496 T>C and CD80 rs7628626 C>A SNPs to explore their potential roles in the etiology of HCC." (PMID 31235485, 2019). "Thus, CD8+CD28+ T cells may exert anti-tumor efficiency among CD8+ T cells." (PMID 30971280, 2019).
tumor (continued). "CD28 is a co-stimulatory molecule that is important for the activation of CD8+T cells, which play an important role in anti-tumor immunity." (PMID 31623615, 2019). "Together, these data suggest that B10G5 enhances tumor response to anti-PD-L1 therapy in part by providing antigen-specific CD8 T cells with NKG2D and CD28 dual co-stimulation." (PMID 31446896, 2019). "It was reported that the central memory T cells showed higher anti-tumor toxicity than the effector memory T cells in vivo, and the stimulation by combined anti-CD3, anti-CD28, IL-7 and IL-15 was reported to improve T cell specific cytotoxicity." (PMID 31044002, 2019). "CD4+CD8αα and CD4+CD8αβ T cell clones were then stimulated for 48 h with anti-CD3/CD28 antibodies and supernatants were harvested to measure levels of antitumor Th1-type cytokines (IFN-γ, TNF-α), as well as of pro-tumor Th2-type cytokines (IL-4, IL-5)." (PMID 30984190, 2019). "The most common costimulatory molecules are 4-1BB and CD28, and depending on the CAR and tumor type, many studies focus on one or the other." (PMID 30804938, 2019). "Exhausted T cells also highly express costimulatory receptors, like ICOS, CD28, 4-1BB shown in this study, so ICB plus co-stimulation agonists targeting these costimulatory receptors are also actively explored in tumor immunotherapy." (PMID 31783783, 2019). "Around the fourth day of culture, TILs start to migrate out of the tumor tissue to form a confluent layer and cluster with the CD3/CD28 beads around the tumor fragments (left)." (PMID 31398192, 2019). "Lifileucel-induced in vitro IFNγ response to antibody coated beads (anti-CD3, anti-CD28, anti-CD137) and serum IP-10 levels post-treatment, correlates with reduction in tumor (Sum of Diameter of target lesions) and/or overall response." (PMID 30400822, 2018). "Investigators have shown that a third generation CAR CD28-z-OX40 helped CCR7 (-) T cells avoid apoptosis and show potent anti-tumor functional efficacy." (PMID 30713539, 2018). "We defined the differentiation stage of the different lung and tumor T cell subsets by analyzing the surface expression of CD45RA, CD28, CD27, and CCR7." (PMID 30505306, 2018). "Following tumour disaggregation using GentleMACS, we initiated TIL cultures by mitogenically stimulating 4 × 106 cells with anti-CD3/anti-CD28 beads and high-dose IL-2." (PMID 30039427, 2018). "CTLA-4 is structurally similar to CD28 and binds to CD80 (B7-1) / CD86 (B7-2) on APCs (or tumor cells) at a higher affinity than CD28, which suggests an interference with T cell activation." (PMID 29988281, 2018). "CD28 CD19-specific CAR-T cells co-transduced with PD-1 DNR demonstrated enhanced in vitro T cell functions and in vivo T cell efficacy with enhanced tumor burden control and prolonged median survival." (PMID 29364163, 2018). "We purified neutrophils from the peritoneal cavity of tumor-bearing Cybb−/− or WT mice and co-cultured them with anti-CD3/CD28-stimulated CD27− γδ T cells." (PMID 29750788, 2018). "CD4+ TIL were stimulated with autologous tumor or dendritic cells (DC), or anti-CD3/CD28 and assayed for cytokine production by ELISA and flow cytometry." (PMID 30400835, 2018). "These inhibitory effects were also observed when splenocytes derived from tumor-free control mice were stimulated with concanavalin A or the combination of anti-CD3 and anti-CD28 antibodies." (PMID 30562962, 2018). "They engineered an MRP1-CD28 bivalent aptamer that was able to bind MRP1-expressing tumors and deliver the CD28 co-stimulatory signal to tumor-infiltrating lymphocytes." (PMID 28325295, 2017). "CD4+ or CD8+ T cells were cultured with or without Ly6G+CXCR2− cells sorted from spleen of normal mice or CXCR2+ MDSCs sorted from spleen of 4T1 tumor-bearing mice under the stimulation of anti-CD3 and anti-CD28 for 3 days." (PMID 29383101, 2017).
tumor (continued). "Different combinations of co-stimulatory proteins (e.g. 4-1BB/CD28, CD28/OX40) were assessed, showing various effects concerning T cell persistence, cytokine release, and tumor regression." (PMID 28496440, 2017). "In the present study, the co-expression of CD28 and CTLA-4 on both tumor cells and tumor-infiltrating lymphocytes (TILs) was detected." (PMID 26918337, 2016). "Splenic CD11b+Gr-1+ cells from 4T1-bearing mice were confirmed to exhibit prototypical MDSC suppressor function defined by potent inhibition of CD3/CD28-driven proliferation of CD4+ and CD8+ T cells (from non-tumor bearing mice) in vitro." (PMID 27929373, 2016). "IL-15 provided similar performance in stimulating CART cell expansion and tumor-lysis functions in vitro than IL-2, but induced a less differentiated phenotype, with higher CD27 and CD28 expression." (PMID 27409425, 2016). "In the IMCG cohort for example, CD28 and CD3 with aging decreased expression of GZMA and GZMB, proteases important in T cell and NK-cell-mediated tumor cell lysis." (PMID 27760559, 2016). "Because anti-CD19/CD28 CAR is more widely used in CAR-T cell therapy, we modified CIKZ cells with anti-CD19/CD28 mRNA CAR to demonstrate the in vivo tumor-killing efficiency of mRNA CAR-modified CIKZ cells." (PMID 27598655, 2016). "We also determined that anti-CD19/CD27 CAR and anti-CD19/CD28 CAR were comparable to each other with respect to cytokine release and cytotoxicity against tumor cells." (PMID 27598655, 2016). "Culturing CD3/CD28-CAR-T in the presence of IL-7 and IL-15 gave the best effector activity while retaining a stem/memory against GD2 tumor antigen." (PMID 26999211, 2016). "The CD28 agonistic aptamer-coated tumor cells were injected subcutaneously in C57BL6 mice as shown in the vaccine calendar, and the tumor growth was monitored by caliper measure." (PMID 26992239, 2016). "For example, tumor cells are believed to promote the expression of CTLA-4, which is a molecule expressed by T cells that competes with CD28 for the co-stimulatory molecule CD80 (B7.1), thereby suppressing T cell activation." (PMID 27092248, 2016). "Moreover, given an adequate number of preexisting active T cells in the Group 1 tumor microenvironment, the balance between CD28/B7 positive and CTLA-4/B7 negative regulatory signals may be overthrown by CTLA-4 blockade, thus evoking excessive immune response and immunity-related toxicity." (PMID 25893809, 2015). "Second-generation CARs, which include intracellular signalling domains for co-stimulatory signals such as CD28 and CD137, have been shown to produce enhanced tumour-regression effects." (PMID 26035842, 2015). "In T-cell proliferation, cytokine secretion and in vivo tumor killing assays, we observed that CAR-mediated CD28 costimulation in 19-28z+ T cells is more potent than CD80 costimulation of 19z1 expressing T cells." (PMID 26110267, 2015). "In vitro studies revealed that knockdown of B7-H3 on tumor cells enhanced T-cell growth and interferon-γ secretion when stimulated by anti-CD3 and anti-CD28 monoclonal antibodies." (PMID 25609202, 2015). "Human T cells engineered to express a chimeric antigen receptor (CAR) recognize and kill tumor cells in a MHC-unrestricted manner and persist in vivo when the CAR includes a CD28 costimulatory domain." (PMID 26110267, 2015). "Tumor-derived CD4 T cells were sorted into Tim-3+ and Tim-3− subsets, and then cocultured with responder cells on anti-CD3/CD28 stimulation for 5 days." (PMID 23526963, 2013). "We recently showed that the aAPC platform induces numerically similar expansion of TIL compared with REM, and these TIL have a “young” CD27+CD28+ phenotype, are enriched for CD8+ T cells, contain fewer Tregs and are tumor-reactive." (PMID 23402380, 2013). "These "young" TILs are tumor-reactive, positively skewed in CD8+ lymphocyte composition, CD28 and CD27 expression, and contain fewer FOXP3+ T cells compared to parallel IL-2 cultures." (PMID 21827675, 2011).
tumor (continued). "Studies have described the presence of B7 costimulatory molecules in tumor cells of NPC, and the corresponding counter-receptor, CD28, in lymphoid cells, implying some communication between T cells and carcinoma cells in the microenvironment of NPC." (PMID 17524139, 2007). "Efficient tumor growth inhibition was observed in the group treated once with CAR-T (CD3z-CD28) cells at EDD11, but not in the group treated twice." (PMID 41596451, 2026). "In the first in ovo tumor challenge study, CAR-T (CD3z-CD28) cells were tested with a single dose of 1 × 105 cells per embryo at each administration, corresponding to an effector-to-tumor ratio (E:T) of 1:1 and 1.67 million cells/kg, either once at EDD11, or twice at EDD11 and EDD14." (PMID 41596451, 2026). "CD8+ CD103+ CD39+ PD-1+ CD28- TRM cells, known for their higher anti-tumour cytokine production, may facilitate the recruitment of less-exhausted peripheral T-cells to the NSCLC tumour site, potentially improving their response to ICIs." (PMID 40361472, 2025). "It appears that upon initial antigen encounter, effector-polarized CAR-T cells, particularly those with CD28 co-stimulation, produce substantial IFNγ, which enhances ICAM-1 expression on tumor cells and facilitates subsequent CAR-T cell infiltration into tumor tissue." (PMID 41154636, 2025). "In TNBC, PD-L1 expression is not merely correlated with but can be directly driven by a tumor-intrinsic CD28-SNRPB2 pathway, which stabilizes Cd274 mRNA." (PMID 41567982, 2025). "Similarly, a biodegradable nanoparticle platform delivering IL-2, anti-CD28, Pam3CSK4, and a NOD2 agonist, was shown to stimulate endogenous tumor-infiltrating T cells and slow tumor growth." (PMID 40948803, 2025). "Similarly, B7 ligands B7-1 (CD80) and B7-2 (CD86) on tumor cells engage CTLA-4 on activated CD8+ T cells, outcompeting CD28 and thereby blocking co-stimulatory signals required for T cell activation, leading to CD8+ T cell anergy." (PMID 41268548, 2025). "In turn, tumor-specific T cells expressing Carmil2QE do not require CD28 engagement and thereby escape to both PD-1 and CTLA-4 inhibition." (PMID 40402149, 2025). "Preclinical studies suggest that combining a CD3-engaging TCE with a CD28 bispecific greatly enhances T-cell proliferation and tumor eradication, without systemic T-cell overactivation, as co-stimulation is restricted to MUC16-positive tumor cells." (PMID 40643516, 2025). "Additionally, TGFB2 methylation correlates inversely with numerous T cell receptor (TCR) signaling components—HLA-D molecules, CD3D, CD28, and LCK—all of which are upregulated in the tumor when TGFB2 is weakly methylated." (PMID 40650134, 2025). "Concomitant quantification of PD-L1-CD80 cis-heterodimers on tumor cells stratifies patients further: where this inhibitory pair is abundant, adding a PD-L1 antagonist liberates both CD80 for CD28 co-stimulation and PD-L1 from PD-1 restraint, amplifying anti-tumor immunity." (PMID 41112277, 2025). "The fact that anti-CD80/86 has a benefit in combination with radiation suggests that at this stage of tumor therapy costimulation through CD28 is not as important as we would anticipate." (PMID 41417245, 2025). "Thus, once the CD19.CD28 CAR-T cells were injected into the mice, they were more likely than the CD19.4–1BB CAR-T cells to immediately initiate tumor killing and prevent tumor growth." (PMID 40568128, 2025). "Moreover, ascites-derived CD4+ T cells and CD8+ T cells exhibited significantly reduced proportions of CD28, with 63.60 ± 10.77% of CD4+ T cells and 16.05 ± 5.57% of CD8+ T cells, compared to PB and tumor samples." (PMID 41221283, 2025). "A key innovation lies in the design of dual- and trispecific antibodies that engage multiple tumor antigens (e.g., BCMA/GPRC5D/CD3 or BCMA/CD3/CD28), thereby mitigating antigen escape and incorporating intrinsic co-stimulatory signaling to sustain T cell activation." (PMID 41470115, 2025).